IL2 (interleukin 2)
Diseases named in the same sentence as IL2 in open-access papers (continued):
Sharing a sentence is not in itself a finding about the gene and the disease.
metastatic melanoma (continued). "Given their immunologic effects, low-dose interleukin-2, granulocyte-monocyte colony stimulating factor and interferon alpha-2b produce durable remissions in patients with metastatic melanoma, and they have been used as postoperative adjuvant therapies." (PMID 17650346, 2007). "A similar "broad activation" principle serves as a rationale for systemic interleukin-2 (IL-2) administration, which is currently used as anti-cancer immunotherapy in renal cell cancer and metastatic melanoma." (PMID 17999770, 2007). "Since its introduction to the clinic in 1985, IL-2 remains the only established immunotherapy approved by the US Food and Drug Administration for the treatment of metastatic melanoma and mRCC." (PMID 16434984, 2006). "Marincola also described a study aimed at characterizing the mechanisms by which systemic administration of high-dose interleukin-2 (IL-2) was effective for the treatment of metastatic melanoma." (PMID 16464241, 2006). "Recent studies of IL-2-based immunotherapy in metastatic melanoma have identified mainly LDH, performance status, number of metastatic sites and sites of metastases as independent prognostic factors." (PMID 16052222, 2005). "Two patients with metastatic melanoma, one in each study, responded (11.8%); both received IL-2 alone." (PMID 8855983, 1996). "Interleukin 6 and C-reactive protein (CRP) were determined prior to IL-2 therapy in sera from metastatic melanoma patients." (PMID 8180022, 1994). "Plasma samples were collected from 20 patients undergoing phase I clinical trial with flavone-8-acetic acid (FAA; 4.8 g m-2 per dose) in combination with recombinant human interleukin-2 (rhIL-2; 6-18 i.u. m-2 per day) for the treatment of metastatic melanoma." (PMID 1419615, 1992). "Some research on fusion proteins of antibody and IL-2 as a payload demonstrated strong anti-cancer activity in various mouse models of cancer, including metastatic melanoma, neuroblastoma, prostate carcinoma, colon adenocarcinoma, non-small cell lung carcinoma, and lymphoma." (PMID 41568361, 2025). "In parallel with the development of targeted therapy, advancements in the understanding of tumor immunology and immune evasion have driven the development of numerous drugs, with interleukin-2 (IL-2) being the first immunotherapy treatment approved for advanced or metastatic melanoma." (PMID 40027067, 2025). "However, such promising results were not obtained in a phase II clinical trial in which 12 patients with unresectable metastatic melanoma received TILs therapy with an even lower IL-2 dose (125,000 IU/kg × 12 days)." (PMID 40458394, 2025). "High-dose interleukin-2 (IL-2) was approved by the U.S. FDA to treat metastatic melanoma in 1998." (PMID 39682188, 2024). "High dose of IL-2 induced striking responses in patients with metastatic melanoma or renal cancer, but unacceptable adverse effects such as capillary leak syndrome (the most severe side effect of IL-2), constitutional symptoms and renal dysfunction were also observed." (PMID 39415291, 2024). "In their study, 20 metastatic melanoma patients received adoptive TIL therapy along with IL-2." (PMID 39337333, 2024). "One such study is the randomized prospective phase II trial (NCT02621021), which is being carried out to find out if patients with metastatic melanoma may experience higher response rates when pembrolizumab is added to TIL/IL-2 therapy." (PMID 39712007, 2024). "IL-2 is one of the FDA-approved immunocytokines for metastatic melanoma and renal cell carcinoma." (PMID 37047449, 2023). "In a phase I clinical trial, among seven patients with metastatic melanoma who were treated with stereotactic body radiation therapy followed by interleukin-2 (IL-2), 71% achieved a complete or partial response compared to 16% that was previously reported in association with IL-2 monotherapy." (PMID 36816935, 2023). "High-dose IL-2 infusions have been approved for the treatment of metastatic melanoma since 1998." (PMID 36676129, 2023).
metastatic melanoma (continued). "In the present study, we treated patients with unresectable or metastatic melanoma with the standard dose of pembrolizumab and escalating doses of IL-2 to determine the safety of the combination and to select a dose of IL-2 for further study in combination with anti-PD-1 therapy." (PMID 36845705, 2023). "Furthermore, IL-2 plays a critical role in priming tumor-infiltrating lymphocytes for the treatment of cancers such as metastatic melanoma and non-small cell lung cancer." (PMID 37256141, 2023). "An ongoing phase II study has the aim of exploring the efficacy of HD IL-2 in combination with low dose ipilimumab followed sequentially by nivolumab in patients with unresectable or metastatic melanoma who had progressed on prior anti-PD1 therapy (NCT04562129)." (PMID 35053435, 2022). "Other than IL-2, IL-18 was also found to be effective to induce the NK cell activity and the expression of CD107a degranulation marker both in metastatic melanoma and control, when used in combination with IL-12 in peripheral blood mononuclear cells from both groups." (PMID 36428682, 2022). "When it was licensed for the treatment of metastatic melanoma and renal cell carcinoma in 1998, interleukin-2 (IL-2), a T-cell growth factor that aids in immunological modulation and T-cell proliferation, became the second anticancer cytokine approved by the FDA." (PMID 35892341, 2022). "IL-12 can be used in combination with IL-2 to successfully control metastatic melanoma progression." (PMID 36428682, 2022). "IL-2 was one of the first FDA-approved cytokines for metastatic melanoma and renal cell carcinoma." (PMID 35884907, 2022). "Previously, we studied patients with metastatic melanoma and mRCC treated with HD-IL2 and undertook sequential immune monitoring using flow cytometry, which revealed changes in immune profiles that were related to IL2 response." (PMID 36923304, 2022). "Therefore, IL-2 therapy is used as treatment in metastatic renal cell carcinoma and metastatic melanoma." (PMID 35628346, 2022). "Some of the therapeutic drugs such as interferon-α (IFN-α) for hairy cell leukemia, interleukin-2 (IL-2) for metastatic renal cancer and metastatic melanoma have been approved by the US Food and Drug Administration (FDA), and has achieved certain remission in some patients." (PMID 35757741, 2022). "IL2, a well-known T-cell growth factor approved for the treatment of metastatic melanoma and renal cell carcinoma, promotes the in situ recruitment and activation of cytotoxic immunocytes and switches the immunosuppressive TME toward antitumor immune responses." (PMID 35799600, 2022). "Interleukin 2 treatment exhibited high grade cardiovascular, gastrointestinal, neurological, pulmonary, hepatic, renal, and hematological toxicities, and it led to deaths in 4% and 2% of mRCC and metastatic melanoma patients, respectively." (PMID 33803078, 2021). "Another study suggested that IL-2 treatment could restore Th1 ⁄ Th2 balance in metastatic melanoma and activate lymphocytes." (PMID 33441929, 2021). "In a murine model of metastatic melanoma, IL-2 immunocytokines targeting GD2 and epidermal growth factor receptor (EGFR) suppressed lung and liver metastases, in addition to prolonging survival, when administered after LAK cell reconstitution in immunocompromised mice." (PMID 33803078, 2021). "TILs have been grown from resected metastatic melanoma lesions in high-dose IL-2." (PMID 34603332, 2021). "As early as 1985, patients with metastatic melanoma were treated with intravenous IL-2." (PMID 34885172, 2021). "Additionally, patients with metastatic melanoma receiving high-dose IL-2 plus the gp100:209-217(210M) peptide vaccine had a higher response rate and longer progression-free survival than single regimen-treated patients." (PMID 33466236, 2021).
metastatic melanoma (continued). "IL2 controlling ITGAM, which in complex with CD14 (both are cell surface markers,), are specific in C10 and this type I cytokine can be associated with durable regression in metastatic melanoma and renal cell carcinoma." (PMID 34238310, 2021). "Similarly, the USFDA approved IFN-α for treatment for hairy cell leukemia and IL-2 for metastatic kidney cancer and metastatic melanoma in 1986 and 1992 respectively, which have been shown to enhance the production of T cells in patients." (PMID 33717106, 2021). "Interleukin-2 (Il-2) has been approved for metastatic melanoma and renal cell carcinoma." (PMID 32188078, 2020). "Finally, a clinical trial evaluated the efficacy of the gp100 combined with high-dose interleukin-2 (IL-2) in patients with metastatic melanoma." (PMID 33080888, 2020). "IL-2 was used for treatment of patients with metastatic melanoma." (PMID 31938023, 2020). "In metastatic melanoma patients, the expression of CD25 on NK cells has been associated with clinical response to anti-PD1 therapy, presumably in part due to increased NK cell sensitivity to IL-2 and thus increased survival and function." (PMID 32517713, 2020). "Clinical use of L19IL2 and L19TNF, the recombinant fusion protein of recombinant monoclonal antibody (L19) with the human recombinant interleukin-2 (IL-2) or the human tumor necrosis factor-alpha in patients suffering from metastatic melanoma is ongoing (ClinicalTrials.gov Identifier: NCT02076633)." (PMID 32422889, 2020). "High-dose ipilimumab (IPI) and high-dose interleukin-2 (IL-2) are approved agents for metastatic melanoma, but the efficacy and safety of the combination are unknown." (PMID 31998643, 2020). "Following the use of IL-2 as a T-cell growth factor in the treatment of patients with metastatic melanoma and renal cell cancer (RCC), manipulation of the host immune system has been suggested to elicit an endogenous reaction capable of mediating cancer regression." (PMID 32610601, 2020). "For instance, IL-2 has been widely used for the treatment of patients with metastatic melanoma." (PMID 31915416, 2019). "Here, we report the results of a phase II study of 12 patients with metastatic melanoma treated with a modified ACT protocol utilizing autologous TIL with preconditioning chemotherapy followed by the administration of subcutaneous IL-2 administered at a low dose of 125,000 IU/kg/day over 12 days." (PMID 30747243, 2019). "In conclusion, results of this trial reveal that the combination of vemurafenib and HD IL-2 in the treatment of BRAF-mutated metastatic malignant melanoma was safe but without added clinical benefit beyond what would be expected with either agent alone." (PMID 30053905, 2018). "The hu14.18-IL-2 immunocytokine containing a humanized anti-GD2 mAb linked to IL-2 was mainly studied as mono-therapy in neuroblastoma and in combination with anti-CTLA-4 plus RT in primary and metastatic melanoma." (PMID 30619269, 2018). "Thus, interleukin-2 (IL-2) is already approved as an in vivo T-cell modulator for the treatment of patients with metastatic melanoma and renal cell carcinoma." (PMID 29568345, 2018). "High dose interleukin-2 (IL-2) was the first agent used in the treatment of metastatic melanoma." (PMID 30788189, 2018). "The use of tumor vaccine or modified T-cell therapy in combination or sequentially with HD IL-2 may be valuable in the treatment of malignancies such as metastatic melanoma and renal cell carcinoma." (PMID 29898784, 2018). "Similarly, high-dose bolus interleukin-2 (IL-2) has FDA approval for metastatic melanoma and renal cell carcinoma, but is challenged by low response rates and notorious toxicities." (PMID 30275839, 2018). "High dose IL-2 has been used in treatment of metastatic melanoma and renal cell carcinoma." (PMID 30400822, 2018).
metastatic melanoma (continued). "The therapy entails initial lympho-depletion followed by administration of ex vivo expanded tumor infiltrating lymphocytes (TILs) and large doses of interleukin 2 (IL-2) and had an approximately 50% response rate in patients with highly advanced and metastatic melanoma." (PMID 28107203, 2017). "In a study done by Rosenberg and his collaborators, 409 patients with either metastatic melanoma or renal carcinoma, were treated with a high-dose of IL-2 (720,000 lU/kg), a complete response was observed in 8.1% patients, and a partial response in 9% patients." (PMID 28927416, 2017). "For example, the administration of high doses of recombinant IL-2 is currently being used to boost T cell activity against metastatic melanoma and other tumors, while low doses of IL-2 are being used to increase Treg function in autoimmune and inflammatory conditions." (PMID 28848546, 2017). "To assess whether patients in the clinic displayed similar changes in surface marker expression, we collected peripheral blood mononuclear cells (PBMCs) from metastatic melanoma patients undergoing systemic high dose IL-2 therapy." (PMID 28428882, 2017). "Fifty-two metastatic melanoma patients were treated with ipilimumab prior to IL-2." (PMID 27660706, 2016). "In this study, we measured the extent of STAT5 and STAT1 activation, proliferative capacity and cytokine production in different peripheral blood lymphocyte subsets from a group of patients with metastatic melanoma in comparison to a cohort of healthy controls upon HD IL-2 stimulation." (PMID 27153543, 2016). "At present, little is known about whether any defects exist in the response of lymphocytes from metastatic melanoma patients to HD IL-2 despite its use in the clinic now for about two decades." (PMID 27153543, 2016). "This could explain the relatively low response rates seen in metastatic melanoma patients in response to HD IL-2." (PMID 27153543, 2016). "A new paradigm for primary systemic treatment for metastatic melanoma has shifted toward immunotherapy including IL-2, anti-CTLA4 monoclonal antibody (ipilimumab), and programmed cell death 1 antibody (anti-PD1), as well as targeted therapies (BRAF or MEK inhibition)." (PMID 25932372, 2015). "Various immunotherapeutic agents such as interleukin-2 (IL-2), ipilimumab, nivolumab, or anti-PD-1L demonstrate a long-lasting survival of fraction of patients, which can eventually translate into the cure of metastatic melanoma." (PMID 26020391, 2015). "A new paradigm for primary systemic treatment for metastatic melanoma has shifted toward immunotherapy, including IL-2 and anti-CTLA4 monoclonal antibody (ipilimumab) as well as programmed cell death 1 antibody (anti-PD1), and molecularly-targeted therapies (BRAF or MEK inhibitors)." (PMID 25815245, 2015). "High levels of VEGF and fibronectin have been associated with lack of clinical response to high dose IL-2 therapy and worse overall prognosis in metastatic melanoma and renal cell carcinoma patients." (PMID 26380086, 2015). "Current approved therapeutic options in the US and Europe for patients with metastatic melanoma include dacarbazine, interleukin-2, ipilimumab, vemurafenib, dabrafenib, and trametinib, but long-term tumor regression using available agents remains out of reach for most patients." (PMID 24726012, 2014). "In the past, several studies have focused on IL-2/chemotherapy combinations in metastatic melanoma." (PMID 25245327, 2014). "In clinical trials, the addition of SBRT to high-dose IL-2, has been shown to be highly effective in patients with metastatic melanoma and renal cell cancer and represents a clinically tenable strategy given that HD IL-2 is approved for use in these malignancies." (PMID 24434638, 2014).
metastatic melanoma (continued). "High-dose interleukin-2 (HD-IL-2) has been reported to induce an objective clinical disease regression in 15 to 17% of patients with metastatic melanoma and renal cell carcinoma, with 6% to 8% of cases experiencing a durable complete response of all metastases." (PMID 25245327, 2014). "Further work at the NCI Surgery Branch reported their experience in 283 patients with metastatic melanoma or metastatic renal cell cancer treated from September 1985 through December 1992 with high-dose bolus IL-2– this series included 149 patients with renal cell carcinoma." (PMID 28326252, 2014). "For instance, IL-2 therapy is widely used in the treatment of metastatic melanoma." (PMID 25380524, 2014). "Thus far, we demonstrated that resveratrol can ameliorate IL-2 toxicity while promoting the effectiveness of IL-2 in metastatic melanoma therapy." (PMID 22532866, 2012). "Another option for the chemotherapy in patients with metastatic melanoma is the use of termozolomide (TMZ) p.o. followed by subcutaneous (s.c.)low-dose interleukin-2 (IL2), granulocyte-monocyte colony stimulating factor (GM-CSF), and interferon-alpha 2b (IFN alpha)." (PMID 22084751, 2011). "Approved treatments for metastatic melanoma include interleukin-2 (IL-2) and chemotherapy." (PMID 21085676, 2010). "The efficacy of intravenously introduced IL-2 in patients with metastatic melanoma or renal cell cancer has been documented in a number of studies, but discerning the appropriate dosage and treatment schedule with immunostimulatory cytokines remains a time-consuming and trying process." (PMID 20936120, 2010). "We have examined the prognostic impact of neutrophils and monocytes in peripheral blood together with other potentially prognostic factors in 321 patients with metastatic melanoma receiving IL-2-based immunotherapy in consecutive clinical trials between 1990 and 2003." (PMID 16052222, 2005). "We aimed to create a prognostic model in metastatic melanoma based on independent prognostic factors in 321 patients receiving interleukin-2 (IL-2)-based immunotherapy with a median follow-up time for patients currently alive of 52 months (range 15–189 months)." (PMID 16052222, 2005). "The unusual high CR rate in metastatic melanoma of 62.5% and the limited toxicity suggest that treatment of skin and soft-tissue melanoma metastases with intralesional injection of IL-2 may be a safe and effective alternative to conventional therapies." (PMID 14583759, 2003). "Therefore, we evaluated the toxicity and efficacy of escalating doses of oral TMZ followed by subcutaneous injections of low-dose IL2, GM-CSF and IFNα in a phase I/II trial in patients with metastatic melanoma." (PMID 12610499, 2003). "Among the numerous interleukins developed for tumor therapy, IL-2, initially called T cell growth factor, holds a significant place as it was the first to receive approval from the U.S. Food and Drug Administration for the treatment of metastatic melanoma and renal cell carcinoma." (PMID 38910324, 2024). "Furthermore, a recent phase 1/2 trial (PIVOT-02) reported an extended PFS and an acceptable rate of grade 3/4 adverse effects in response to the administration of bempegaldesleukin (a CD122-preferential interleukin 2 pathway agonist) plus nivolumab as first-line treatment for metastatic melanoma." (PMID 35493449, 2022). "Studies on metastatic melanoma demonstrated that autologous tumour-infiltrating lymphocytes (TILs), ex vivo-expanded in the presence of interleukin-2 (IL-2) and then reinoculated into the patients, may be exploited to induce a long-lasting (up to 3 years) disease regression." (PMID 35884372, 2022). "Similarly, low-dose chemobiotherapy with temozolomide, GM-CSF, IFN-α2β, and recombinant IL-2 produced clinical responses in patients with metastatic melanoma and may protect against the development of brain metastases." (PMID 33466236, 2021).